CHI3L1 (chitinase 3 like 1)
Diseases named in the same sentence as CHI3L1 in open-access papers (continued):
Sharing a sentence is not in itself a finding about the gene and the disease.
brain astrocytoma (1 paper, 2025). A astrocytoma (excluding glioblastoma) that involves the brain. "Other studies have shown that CHI3L1 can stimulate the phosphorylation of ERK1/2 in human renal epithelial cell lines (293 cells) and human brain astrocytoma cells (U373 and U87 MG cells), which leads to cell proliferation." (PMID 40260255, 2025).
bronchiolitis (1 paper, 2024). Inflammation of the bronchioles characterized by swelling of the bronchioles and mucus accumulation. "Serum Chi3l1 levels act as a critical biomarker for bronchiolitis obliterans, which further contributes to distinguishing exacerbation of postinfectious bronchiolitis obliterans from acute bronchiolitis in young children." (PMID 39769202, 2024).
cardiac sarcoidosis (1 paper, 2025). Sarcoidosis affecting the tissues of the heart. "In the context of cardiac sarcoidosis, the upregulation of CHI3L1 within granulomas may help create a pro-fibrotic microenvironment that supports the persistence of M2 macrophages and drives fibrotic expansion, ultimately contributing to adverse cardiac remodeling and dysfunction." (PMID 40521183, 2025).
cervical (1 paper, 2014). "Not only the allele distribution of CHI3L1 SNPs but also CHI3L1 risk haplotypes, AACC and AACT, correlated with the susceptibility to cervical pre-cancerous lesions and invasive cancer in the present study." (PMID 25203433, 2014).
Chronic colitis (1 paper, 2015). A chronic inflammatory disease of the large intestine (colon, cecum and rectum). "We also show that the analysis of CHI3L1 levels in non-invasively collected feces serves as a convenient and reliable modality to predict the neoplastic changes during the course of chronic colitis." (PMID 26431492, 2015). "Here we demonstrate that the dynamic process of the neoplastic progression of IECs in chronic colitis is regulated by the increased production of CHI3L1, which reciprocally regulates the expression of S100A9 under inflammatory conditions." (PMID 26431492, 2015). "In this study, we demonstrate that CHI3L1 expression in IECs can provide a protection against chronic colitis by promoting the survival and proliferation of IECs both in vitro and in vivo." (PMID 26431492, 2015). "In addition, Brp39 KO mice exhibited much more severe clinical symptoms as judged by diarrhea, bloody stool and hunching posture, especially during the second and the third cycles of DSS treatments, suggesting that the lack of CHI3L1 contributes to the exacerbation of chronic colitis." (PMID 26431492, 2015).
coagulopathy (1 paper, 2021). "The current study unveiled an important function of Chi3l1 in promoting platelet recruitment into the liver after APAP overdose, thereby playing a critical role in exacerbating APAP-induced coagulopathy and liver injury." (PMID 34110284, 2021).
dependence (1 paper, 2025). "The identification of clinically validated biomarkers (GFAP, UCHL1, CHI3L1) in the dependence group suggests potential for developing diagnostic and monitoring tools for alcohol-related brain injury." (PMID 41292811, 2025).
diabetic foot ulcers (1 paper, 2023). "In chronic wounds, such as healing wounds with diabetic foot ulcers, the fibroblasts overexpress CHI3L1, MMPs, and TNFAIP6, similar to the hub genes in this study." (PMID 37685578, 2023).
diabetic retinopathy (1 paper, 2015). "Several identified genes with altered DNA methylation in cases with PDR, such as TNF, CHI3L1, and CHN2, encode proteins with previous known function in diabetic complications and/or diabetic retinopathy." (PMID 26248552, 2015).
diarrhoea (1 paper, 2022). "Some of the DEGs in diarrhoea-susceptible sheep, enriched in GO terms and sub-network analysis, included IL-6, LOC101121216 (serum amyloid A), SIGLEC1, CHI3L1, S100A9, CD14, CD68, CD86, Ovar-DRB1, IL1RL1, LOC101103238 (CXCL5), CCL22 and IL1RN." (PMID 35576023, 2022).
esophageal tumor (1 paper, 2021). "In accordance with these findings, our analysis revealed an upregulated level of CHI3L1 in esophageal tumor tissues." (PMID 34612767, 2021). "The analysis of immunological signatures and CHI3L1 expression indicated that CHI3L1 level was highly correlated with increased expression of macrophage signature genes in esophageal tumor tissues." (PMID 34612767, 2021). "In summary, our study revealed the upregulation of CHI3L1 in esophageal tumor tissues." (PMID 34612767, 2021). "Importantly, we showed a strong positive correlation between macrophage signatures and CHI3L1 expression level, indicating that CHI3L1 overexpression may favor macrophage recruitment in esophageal tumor tissues." (PMID 34612767, 2021). "CHI3L1 overexpression may favor macrophage recruitment in esophageal tumor tissues." (PMID 34612767, 2021).
falciparum malaria (1 paper, 2014). "Plasma levels of CHI3L1 were quantified in a case–control study of Ugandan children presenting with Plasmodium falciparum malaria." (PMID 25047113, 2014). "In children presenting with falciparum malaria, CHI3L1 levels were increased in SMA and CM versus UM (p < 0.001)." (PMID 25047113, 2014).
Fever (1 paper, 2025). Body temperature elevated above the normal range. "Serum CHI3L1 levels in the KD group were significantly higher than those in the fever control group and healthy group." (PMID 40044787, 2025).
Fulminant hepatitis (1 paper, 2022). Acute hepatitis complicated by acute liver failure with hepatic encephalopathy occurring less than 8 weeks after the onset of jaundice. "UC-MSC can suppress T cell activation in fulminant hepatitis through chitinase 3-like protein 1 (CHI3L1) and NF-κB signaling." (PMID 35406638, 2022).
Graves disease (1 paper, 2024). Graves' disease is an autoimmune disorder that leads to overactivity of the thyroid gland (hyperthyroidism).It is caused by an abnormal immune system response that causes the thyroid gland to produce too much thyroid hormones. "Finally, Graves’ disease (GD), an autoimmune thyroid disease, is associated with increased levels of Chi3l1." (PMID 39769202, 2024).
hepatic porphyria (1 paper, 2023). A group of metabolic diseases due to deficiency of one of a number of liver enzymes in the biosynthetic pathway of heme. "As high-dose treatment with 5-ALA may not be applicable to patients with acute hepatic porphyria or lead poisoning 57, additional treatment with CHIL3/CHI3L1 could provide extra efficacy to mitigate HIR injury." (PMID 37771779, 2023).
HIV-associated neurocognitive disorder (1 paper, 2024). HIV-associated neurocognitive disorder (HAND) remains a common complication of HIV infection in the combination antiretroviral therapy (ART) era. "Most of the other 30 candidate protein biomarkers had been described in various other neuroinflammatory or neurodegenerative afflictions, e.g. CHI3L1, also known as YKL-40, in the context of HIV-Associated Neurocognitive Disorders (HAND)." (PMID 38962007, 2024).
influenza (1 paper, 2025). An acute viral infection of the respiratory tract, occurring in isolated cases, in epidemics, or in pandemics; it is caused by serologically different strains of viruses (influenzaviruses) designated A, B, and C, has a 3-day incubation period, and usually lasts for 3 to 10 days. "Future investigations into the strength of CHI3L1 as a predictor for influenza severity should continue to account for age as a factor." (PMID 41488910, 2025). "In influenza cases, longer-term hospitalization and ICU admission could be predicted based on two cytokines, CHI3L1 and sTNFR1." (PMID 41488910, 2025).
Kawasaki disease (1 paper, 2025). A rare inflammatory disease characterized by an acute febrile, systemic, self-limiting, medium-vessel vasculitis primarily affecting children. "Our findings indicate elevated levels of CHI3L1 in both complete and incomplete Kawasaki disease, with a strong positive correlation between CHI3L1 levels and various inflammatory markers." (PMID 40044787, 2025). "Chitinase 3-like protein 1(CHI3L1) has been found to be a biomarker for inflammatory diseases, but the diagnostic value of Kawasaki disease (KD) is not investigated." (PMID 40044787, 2025).
keloid (1 paper, 2023). An irregularly shaped, elevated mark on the skin caused by deposits of excessive amounts of collagen during wound healing. "Five hub genes were linked to keloid recurrence, including CHI3L1, IL1RN, MMP7, TNFAIP3, and TNFAIP6." (PMID 37685578, 2023). "In the present study, the hub genes (CHI3L1, IL1RN, MMP7, TNFAIP3, and TNFAIP6) were mainly involved in the regulation of inflammatory response, IL-17 signalling pathway, and TNF signalling pathway, which is consistent with previous findings in keloids." (PMID 37685578, 2023). "The qRT-PCR experiment was used for detecting the differential expression of five hub genes (CHI3L1, IL1RN, MMP7, TNFAIP3, and TNFAIP6) in recurrent and non-recurrent keloid tissues." (PMID 37685578, 2023).
leprosy (1 paper, 2020). Leprosy is a chronic infectious disease affecting primarily the skin and peripheral nervous system. "The other, meanwhile, was observed primarily in a single leprosy patient and was defined by genes involved in extracellular proteolysis (LYZ, CHIT1, and CHI3L1)." (PMID 33053333, 2020).
leptospirosis (1 paper, 2016). A contagious bacterial infection caused by spirochetes of the genus Leptospira. "Additionally, lower RANTES levels and higher CHI3L1 serum levels were independent risk factors for death in patients with leptospirosis." (PMID 27812211, 2016). "Additionally, we identified CHI3L1 and RANTES, as new risk factors for death from leptospirosis." (PMID 27812211, 2016). "Together, these data suggest CHI3L1, IL-18, and HGF represent new potential prognostic and therapeutic strategies for leptospirosis." (PMID 27812211, 2016).
liver dysfunction (1 paper, 2020). "The expression levels of CHI3L1 in good liver function group were lower than those in liver dysfunction group (P < .001)." (PMID 31916309, 2020).
lung adenoma (1 paper, 2022). A benign, well circumscribed epithelial neoplasm that arises from the bronchus or the lung parenchyma. "Histological analysis of metastatic lung adenomas showed that anti‐Chi3L1 antibody‐treated mice cells had a low‐density distribution, but the vehicle‐treated mice cells were densely distributed." (PMID 34861103, 2022).
mesenchymal tumors (1 paper, 2020). "High expressions of CHI3L1, CD44, SERPINE1, and CTGF, typical of mesenchymal tumors, were also observed." (PMID 32171051, 2020).
Migraine (1 paper, 2024). "The elevation of Chi3l1 levels in migraine patients suggests the presence of neurovascular inflammation in the pathogenesis of migraine." (PMID 39769202, 2024). "Migraine is a neurovascular disorder, and serum Chi3l1 levels are significantly higher in migraine patients than in controls." (PMID 39769202, 2024).
myeloproliferative neoplasm (1 paper, 2026). A clonal hematopoietic stem cell disorder, characterized by proliferation in the bone marrow of one or more of the myeloid (i.e., granulocytic, erythroid, megakaryocytic, and mast cell) lineages. "We found higher CHI3L1 levels in patients with myeloproliferative neoplasm with MF than in those without MF." (PMID 41937713, 2026).
nasal polyp (1 paper, 2024). "This discovery underscores the central role of CHI3L1 in contributing to fibrinolytic system imbalance and nasal polyp formation in ECRS." (PMID 38975344, 2024). "CHI3L1 contributes to fibrin deposition by impairing the fibrinolytic system during nasal polyp formation." (PMID 38975344, 2024).
nasopharyngeal carcinoma (1 paper, 2025). A carcinoma arising from the nasopharyngeal epithelium. "In humans, CHI3L1 expression is up-regulated in the tissues of numerous inflammatory disorders and multiple cancers, including the EBV-associated (LMP1-expressing) cancer nasopharyngeal carcinoma (NPC)." (PMID 40769579, 2025).
neuritis (1 paper, 2023). A neuropathy arising from inflammation of one or more nerves. "CHI3L1 has been studied as a biomarker candidate for the early screening of neuritis and examination of AD and is high in the serum of patients with AD and the CFS of patients with MS." (PMID 36797805, 2023).
neurofibromatosis (1 paper, 2022). A hereditary neoplastic syndrome in which tumors grow in the nervous system. "The mesenchymal type shows high expression of chitinase-3-like protein 1 (CHI3L1) and tyrosine-protein kinase Met (c-Met), with neurofibromatosis type 1 (NF1) mutation/deletion or low expression of NF1." (PMID 35267480, 2022).
neuropathies (1 paper, 2023). "In fact, the CHI3L1 plasma levels were increased in the evaluated MND mimics (including acute myelopathy, radiculopathies, and neuropathies) compared with the MND patients and HCs." (PMID 36983366, 2023). "Moreover, the CHI3L1 levels were statistically significantly higher in the HSP patients compared with the MND patients, likely due to the high frequency of neuropathies in HSP, in which there is usually an inflammatory component." (PMID 36983366, 2023).
Opportunistic infection (1 paper, 2015). An infection that is caused by a pathogen that would generally not be able to cause an infection in a host with a normal immune system. "In order to show a modulation of mammalian chitinase expression as an alternative effective measure to prevent opportunistic infection in the wake of burn injury, we evaluated a WT mouse model in which high-dose anti-CHI3L1 antibody was given simultaneously with burn injury." (PMID 26528713, 2015). "Here, a link between CHI3L1-expression and the clinical outcome of opportunistic infection in the context of burn injury could be further established using CHI3L1 knock-out models." (PMID 26528713, 2015).
pancreatitis (1 paper, 2024). Inflammation of the pancreas. "Elevated serum Chi3l1 levels can be used for diagnosing pancreatitis, and macrophages may be involved in the pancreatic microenvironment during disease progression." (PMID 39769202, 2024).
parasitic infections (1 paper, 2025). "We discuss how adjuvants engaging this pathway might enhance protective TH2 immunity to parasitic infections while drugs that block the activity of Chi3l1 in DCs and CD4 T cells might prevent damaging TH2 responses in the settings of allergic inflammation." (PMID 41012147, 2025).
PEComas (1 paper, 2025). "PEComas are also characterized by specific transcriptomic features of the overexpressed DAPL1, MLANA, SULT1C2, GPR143 and CHI3L1 genes, as well as epigenetic features of lysosomal and melanocyte proteins as biomarkers." (PMID 40989692, 2025).
polyp (1 paper, 2022). A usually exophytic mass attached to the underlying tissue by a broad base or a thin stalk. "However, CXCL5 and CHI3L1 were both increased in the subgroup of infection in both CRC and polyp patients." (PMID 35646113, 2022). "For STC2 and CHI3L1, no significant change was observed in polyp patients in comparison with healthy controls (upper)." (PMID 35646113, 2022).
psychosis (1 paper, 2024). "Chi3l1 can also serve as a biomarker in other psychoses, such as delirium, drug-resistant epilepsy, and first-episode psychosis." (PMID 39769202, 2024).
pulmonary embolism (1 paper, 2021). The obstruction of the pulmonary artery or one of its branches by an embolus, sometimes associated with infarction of the lung. "In addition to being markers of inflammation and angiogenesis, HGF is associated with thrombosis and pulmonary embolism, while CHI3L1 is known to promote coagulation by inducing the expression of TF." (PMID 34262673, 2021).
pulmonary oedema (1 paper, 2023). "CHI3L1 has been identified in altitude induced pulmonary oedema and the response of lung tissue to inflammation in humans." (PMID 36717599, 2023).
Renal atrophy (1 paper, 2023). Atrophy of the kidney. "Specifically, previous studies identified CXCL8 as a DEG in IF/TA patients and Chi3l1 was upregulated in a mouse model of renal atrophy." (PMID 37623492, 2023).
Respiratory insufficiency (1 paper, 2022). "Cox regression analysis revealed that CHI3L1 levels predict primary outcome independently of age, sex, comorbidities, degree of respiratory insufficiency and systemic inflammation or time from symptom onset to sampling (p < 0.0001)." (PMID 35534648, 2022).
Schistosoma haematobium infection (1 paper, 2025). "Some studies have reported increased YKL-40 in children with Schistosoma haematobium infection and changes in histone acetylation at the promoter of the YLK-40-encoding gene (CHI3L1) have been associated with specific IgE levels to Ascaris." (PMID 40943268, 2025).
silicosis (1 paper, 2022). Silicosis is a respiratory disease caused by breathing in (inhaling) silica dust. "For the first time, we found that cellular adhesion molecules (CAM), such as Gm2a, CHI3L1, LCN2, THBD, NADPH oxidase (NOXs) and vacuolar-ATPase are involved in pathogenesis of silicosis." (PMID 34991559, 2022).
spondylitis (1 paper, 2024). The inflammation of a vertebra. "In patients with spondylitis, higher Chi3l1 levels are accompanied by higher disease activity scores, indicating that Chi3l1 can be used as a useful biomarker for the early diagnosis of this disease." (PMID 39769202, 2024). "In addition, treatment with TNFα inhibitors can change Chi3l1 levels in spondylitis patients, further confirming the utility of this protein in monitoring therapeutic efficacy." (PMID 39769202, 2024).
viral meningitis (1 paper, 2019). Inflammation of the membranes surrounding the brain and spinal cord due to a viral infection. "In fact, it has been demonstrated that an IL-13 pathway activation is related to high CHI3L1 levels with differential patterns in bacterial or viral meningitis, suggesting the involvement of CHI3L1 in heterogeneous inflammatory pathways." (PMID 31608004, 2019).